MMP9 (matrix metallopeptidase 9)
Diseases named in the same sentence as MMP9 in open-access papers (continued):
Sharing a sentence is not in itself a finding about the gene and the disease.
cancer (continued). "Validity from several studies has revealed that MMP-9 and CCR7 could be good predictors and reliable indicators of cancer metastasis." (PMID 37600570, 2023). "δ-tocotrienol has been reported to inhibit cancer cell invasion by downregulating MMP-2 and MMP-9." (PMID 38069361, 2023). "Finally, to explore the clinical relevance of SHN3, we investigated the prognostic value of SHN3, together with IL13Rα2, PTP1B and MMP9 in GBM and other cancers using the Betastasis (REMBRANDT), PRECOG and the Human Protein Atlas (HPA) databases." (PMID 37963919, 2023). "However, in colon adenocarcinoma, DMP-1 binds and activates proMMP-9 and bridges MMP-9 to CD44, αvβ3 and αvβ5 integrins on the cell surface, enhancing cancer cell invasion and metastasis." (PMID 36765749, 2023). "Cryptolepine had no obvious effects on MMP2 and MMP9 expression in unstimulated cells but significantly reduced WNT3a-induced expression of these genes, confirming the selectivity of cryptolepine for cancer cells with hyperactive WNT signaling." (PMID 37513937, 2023). "High levels of monomeric forms of LCN2 and MMP9, and LCN2‐MMP9 heterodimers are secreted into the extracellular space, and their levels seem to correlate with the aggressive behaviour of neoplastic cells in several types of cancer." (PMID 37753805, 2023). "Moreover, EVs enriched in TNF1α, TGFβ, and IL-6, isolated from hypoxic human prostate (PC3) cancer cells, increased MMP-2, MMP-9, fibronectin, and collagen deposition and stimulated the recruitment of CD11b myeloid cells at the PMN." (PMID 37350937, 2023). "Similar types of MMPs are increased in both cancers, namely, MMP-1, MMP-2, MMP-9, and MMP-11." (PMID 36982551, 2023). "The content of MMP-9 is enhanced in comparison with MMP-2, particularly in HG cancer tissue." (PMID 36979935, 2023). "Collectively, these results indicate that when the biological processes are deflected as in cancer or preecalmpsia, CLU may regulate either the aggressive behaviour of cancer cells or the EMT of trophoblast cells via regulation of MMP9 activity." (PMID 37685987, 2023). "Thus, matrix-degrading proteases, such as MMP-2, MMP-9, MMP-14 (MT1-MMP), and MMP-16 (MT3-MMP), were reported to be required for EMT progression of different cancer types." (PMID 36766694, 2023). "MMP‐9, another member of the MMP family, has been identified as a biomarker for various cancers." (PMID 37697969, 2023). "Because cancer stem cells and matrix metalloproteinases play a key role in carcinogenesis, CD44, MMP-2, and MMP-9 may be the potential prognosticators for RCC." (PMID 36831550, 2023). "MMP-9 expression is modulated by various physical stimulators such as PMA, and PMA has now been well considered as one of the most common agents as a cancer initiator that enhances MMP-9 expression; therefore, PMA was used in this study as a stimulating agent of BC cells." (PMID 37372062, 2023). "Furthermore, cancer cells treated with EA demonstrated a notable reduction in the secretion of matrix metalloproteinase (MMP)-2 and MMP-9." (PMID 38002335, 2023). "When cancer cells are co-cultured with macrophages (THP-1 cells), the expression of LCN2 and MMP-9 has been found to be induced in ADAM8-KO cells, indicating that macrophage signal transduction can override ADAM8-driven intracellular signal transduction in PDAC cells." (PMID 36910158, 2023). "Additionally, the upregulation of MTDH increased the invasion of cancer cells by upregulation of matrix metalloprotease enzymes (MMPs), specifically MMP-2 and MMP-9." (PMID 36902125, 2023). "MMP9 is one of several tissue-remodeling enzymes capable of enzymatically breaking down ECM to facilitate cell migration, invasion, and wound healing, and is a surrogate marker for invasion of cancer cells." (PMID 36671668, 2023).
cancer (continued). "Our results indicated that cancer progression was potentiated by testosterone treatment and attenuated by 5α-reductase inhibition, leading to alterations in expression of cancer protein markers, including Bcl-2, MMP2, and MMP9." (PMID 36800968, 2023). "In our study, MMP9, a hub gene and upregulated DEG between uLMS-normal myometrium and uLMS-ULM cohorts, was part of the “negative regulation of apoptotic process” GO BP category, as well as “transcriptional misregulation in cancer” KEGG pathway enrichment." (PMID 37373974, 2023). "The principal MMPs involved in cancer are MMP-2, MMP-9, and, most notably, MMP-14." (PMID 36766694, 2023). "In our study, Dex reduced the formation of NETs and the expression of MMP-3 and MMP-9, which might retard the EMT of cancer clinically." (PMID 36910600, 2023). "Another study showed that insufficient thermal ablation can facilitate the growth and metastasis of residual hepatic VX2 carcinoma cells owing to the induction of over-expressions of VEGF, proliferating cell nuclear antigen (PCNA) and matrix metalloproteinase-9 (MMP-9)." (PMID 36650834, 2023). "Among them, MMP-2 and MMP-9 are highly-expressed in malignant tumors, and have been proved to have participated in degradation of the ECM, a crucial component of the basal membrane, leading to cancer metastasis." (PMID 35812733, 2022). "CA reveals action against numerous cancers, inhibiting the exaggerated creation of ROS and supporting cancer cell destruction via DNA oxidation and angiogenesis by acting to decrease VEGF-mediated vascularization and repression of MMP-2 and MMP-9." (PMID 35355732, 2022). "Moreover, MMP2 and MMP9, which were reported to be downstream of SKA1 or TRPV2 in many other cancers, were found to be downregulated in ESCC cells when SKA1 or TRPV2 was knocked down by siRNAs." (PMID 35813298, 2022). "Likewise, Dox-induced chemoresistance was associated with alterations in cellular migration and invasion, which are key cancer hallmarks, coupled with changes in focal adhesion kinase (FAK) activation and secretion of matrix metalloproteinase-9 (MMP-9)." (PMID 36552834, 2022). "They show that ARF1 stimulates the maturation of invadopodia, the release of shedding microvesicles and the activity of matrix metalloproteinase-9 (MMP-9), which promotes the degradation of the extracellular matrix (ECM) and, consequently, cancer cells invasion." (PMID 35805075, 2022). "In addition, PPP4C promotes the expression of matrix metallopeptidase (MMP)-2 and MMP-9 through the PI3K/AKT signaling pathway, thus promoting the invasion and metastasis of cancer cells." (PMID 34964699, 2022). "Carvacrol decreased cancer cells proliferation and apoptosis via decreasing matrix metalloprotease (MMP‐2, MMP‐9) expressions while downregulating the Bcl‐2 expression and inducing phosphorylation of extracellular regulated protein kinase and protein kinase B(p‐Akt) at the molecular level." (PMID 36348778, 2022). "Interactions between mucin 4 (MUC4) and the epidermal growth factor receptor (EGFR) are involved in carcinogenesis, and may lead to matrix metalloproteinase-9 (MMP9) overexpression, exacerbating cancer cell invasiveness." (PMID 36400876, 2022). "The effect of sorafenib, bevacizumab, panitumumab, ramucirumab, sorafenib-bevacizumab, sorafenib-panitumumab and sorafenib-ramucirumab on the relative gene expression of CASPASE3, MMP-9, VEGFR2 and EGFR in HepG2 cancer cells was determined by RT-PCR using GAPDH as a normalizer." (PMID 36284117, 2022). "Furthermore, we adopted gain- and loss-of-function experiments, which demonstrated that miR-331-3p promotes the proliferation, migration, and invasion of PC cells, and also augments the expression of cancer cell metastasis markers, MMP-2 and MMP-9." (PMID 35510828, 2022).
cancer (continued). "We hypothesised that MMP2 and MMP9, both of which are relevant for ECM degradation, may be necessary for peritoneal invasion and cancer cell colonisation." (PMID 35954423, 2022). "The results show that both pulse-based beverages were able to significantly (p < 0.05) reduce MMP-9 activity and cancer cell migration of HT-29 cells, while not reducing HT-29 cell proliferation in a significant manner." (PMID 35911116, 2022). "Additionally, TP73 antisense RNA 1 (TP73-AS1) promotesovarian cancer cell proliferation and metastasis via modulation of matrixmetallopeptidase 2 (MMP-2) and matrix metallopeptidase 9 (MMP-9)." (PMID 35129574, 2022). "In addition, it has been shown that the JNK pathway can promote cancer invasion and metastasis by boosting the expression of other MMP family members such as MMP7 and MMP9, which are induced by the activation of the downstream signaling cascade." (PMID 35409206, 2022). "Moreover, the MMP-9 promoter region contains an NF-kB binding site, indicating that the NF-kB transcription factor can play a role in MMP-9 activation in cancer progression." (PMID 35682652, 2022). "Indeed, we believe that the TLM_CFM-F_OSM combination’s superior anti-cancer properties against NSCLC lung tumors are due to increased TGF-β and MMP-9 expression as well as increased CFM-F penetration into the tumors in this study." (PMID 35745729, 2022). "Yang demonstrated that TP could reduce the expression of human fibrosarcoma HT-1080 cell matrix metalloproteinase-9 (MMP-9), thereby inhibiting cancer metastasis to a certain extent." (PMID 35443712, 2022). "Cancer cell invasion and migration into adjacent tissues are mediated by MMP-2 and MMP-9." (PMID 35458783, 2022). "The increase of several MMPs' expression and enzymatic activity, such as MMP-1, MMP-2, MMP-3, MMP-7, MMP-9, MMP-10, and MMP-14, correlates with the aggressiveness of different types of cancer, which leads to consider them as prognostic markers and targets of new therapeutic strategies." (PMID 36213817, 2022). "The reduction in MMP9 has confirmed the Ap-CH-BSA-FANPs’ anti-proliferative effect against HePG-2 cells, and thus it may prevent cancer metastasis in vivo." (PMID 35745733, 2022). "In addition, accumulating research showed that MDSCs have potent mechanisms to promote cancer growth (via downregulation of IFN-γ and expression of MMP9) and metastasis (via TNFα, TGFβ, CXCL2 and S100A8/9) by establishing an immunotolerant environment." (PMID 35211124, 2022). "Similar results have been reported, where protein extracts from chickpea and lupin reduced MMP-9 activity and cancer cell migration but did not exert cellular toxicity; hence, cell proliferation remained essentially unaltered." (PMID 35911116, 2022). "Furthermore, downregulation of GRP78 by ISL inhibited TGF-β1 secretion from the cancer cells and prevented the activation of CAFs and the inhibition of IL-6, TGF-β1, and MMP-9 by CAFs." (PMID 35740372, 2022). "Additionally, P38-mediated signaling was shown to regulate the expression of MMP1, MMP2, MMP9, and MMP13 in multiple cancer cell lines." (PMID 35409206, 2022). "It has been reported that IL-32 could promote the metastasis of cancer cells by up-regulation the expression of MMP2 and MMP9." (PMID 35428295, 2022). "However, MMP members that have a major role in cancer cell migration and invasion include MMP-2 and MMP-9." (PMID 36605288, 2022). "Its effectiveness in cancer is mediated by inhibition of COX-2, MMP-9, and NF-kB." (PMID 36551934, 2022). "The upregulation of MMPs (MMP2, MMP9, and MMP13) was also reported in cancers overexpressing IL-32 along with other EMT markers including vimentin, Slug, Snail, and ZEB1, as well as they are well known for their contribution to cancer metastatic." (PMID 35281008, 2022). "Melatonin could inhibit cancer cell growth and downregulate matrix metallopeptidase 9 (MMP-9) and fibroblast growth factor 19 (FGF19) to inhibit cancer cells’ invasion and migration." (PMID 35409137, 2022).
cancer (continued). "To sum up, we concluded that by targeting MMP9, TRIM66 could exert a cancer-promoting role in the progression of NSCLC cells." (PMID 35912155, 2022). "This inflammatory response towards cancer cells supports the infiltration of neutrophils, which promotes cancer progression via the secretion of transforming growth factor-β (TGF-β), tumor necrosis factor (TNF)-α, metalloproteinase 9 (MMP9), reactive oxygen species (ROS), and nitric oxide (NO)." (PMID 36142615, 2022). "The matrix metalloproteinase 9 (MMP9) is also responsible for cell growth and cancer metastasis." (PMID 36232606, 2022). "In a similar way, MMP9 was shown to regulate the activity of nerve growth factor (NGF)-induced transmembrane receptor tyrosine kinase A (TrkA), EGFR/HER, and insulin receptor (IR) signaling in cancer cells." (PMID 35406619, 2022). "MMP-9, MMP-14 and MMP-2 have been found to directly regulate angiogenesis, and MMP-9 has been documented to be a key mechanism of the “angiogenic switch” in cancer progression." (PMID 34830354, 2021). "Further, our co-expression analysis also showed that key EMT-related factors such as MMP2, MMP9, CDH2, TGFB1, and VIM were highly expressed when CHN1 was highly expressed, while CDH1 was expressed at lower levels, suggestive of a potential cancer-promoting function of CHN1." (PMID 34152250, 2021). "In most adult tissue, SIX1 is little expressed; however, in some cancer tissues, the re-expression of SIX1 promoted cellular proliferation, migration and stem cell-like features by regulating cyclins and matrix metalloproteinase 9 (MMP9)." (PMID 34513929, 2021). "Studies also showed the phlorotannins may also protect the cancer cell by the inhibition of ROS-generating MMP-2 and MMP-9 via the NF-κB pathway." (PMID 34336128, 2021). "Recent studies suggested that the expression of MMP-9 and TIMP3 could be modulated by miR-221 in other human cancer cells." (PMID 33730072, 2021). "Besides, MMP-9 is a crucial enzyme of MMPs which regulates the degradation of the main constituent of the extracellular matrix (ECM) and is deeply involved in cancer invasion and metastasis." (PMID 34690755, 2021). "Collectively, these results suggest tumoral mRNA expression of MMP1, MMP9, COL1A1 and LAIR1 significantly impacts survival of cancer patients, and therefore led to the hypothesis that MMP generated collagen I fragments might activate LAIR-1." (PMID 34691040, 2021). "Additionally, to metastasize to other organs, cancer cells invade the extracellular matrix by increasing MMP-2 and MMP-9 activity." (PMID 33806109, 2021). "There is still no available antineoplastic drug targeted to MMP-9 because the cytotoxic effect was not sufficiently strong to kill cancer cells and have low solubility." (PMID 34181339, 2021). "The relationship and distribution of telocytes (green) and MMP9 (red) in the para-cancer tissues are disparate between non-metastasis (c) and metastasis (d) samples as determined by immunofluorescence staining." (PMID 34376644, 2021). "Because STAT3 regulates genes that promote cancer cell survival, proliferation, and invasion, we next tested mRNA expression changes of previously established STAT3 target genes, BCL2L1, BIRC5, CCND1, and MMP9 after short-term Olaparib exposure." (PMID 34956861, 2021). "miR-210 inhibitor attenuated the “anti-cancer” effect of sevoflurane and HIF-1α expression induced by sevoflurane, and miR-138 or miR-335 inhibitors reversed the “anti-cancer” effect of desflurane and HIF-1α or MMP9 expressions induced by desflurane." (PMID 33919449, 2021). "MMP9 has the capacity to degrade gelatin and type IV, V, and XI collagen, which form the barrier of the ectracellular matrix (ECM) and participate in cancer metastasis." (PMID 34376644, 2021).
cancer (continued). "In cancer cell lines BCL2 overexpression seems able to promote cell migration, increasing metastatic potential, by regulating Ca2+ homeostasis and by indirectly inducing the production of MMP-9, able to detach leukemic cells from their extracellular matrix." (PMID 33596632, 2021). "Moreover, several studies have reported that EGCG offers potential protection from neurodegeneration or can be considered an inhibitor of cancer cell metastasis via the inhibition of the expression and activity of several proteins such as MMP-2 and MMP-9." (PMID 33498927, 2021). "Although both sevoflurane and desflurane provide “anti-cancer” effects through HIF-1α and MMP9 changes, the regulatory mechanisms of HIF-1α and MMP9 via miRNAs may be difference from one to the other inhalational anesthetics." (PMID 33919449, 2021). "Various in vitro and in vivo assays highlight that ginsenosides including compound K (CK), Rg1, Rg3, Rh1, Rh2 and Rd reduced metastatic abilities of various tissue-specific cancer cells by down-regulating the transcriptional expressions of several MMPs (MMP-1, MMP-2, MMP-3, MMP-7, MMP-9 and MMP-13)." (PMID 33671187, 2021). "Since the relationship between Let‐7i with several target genes including MMP9, C‐Myc and PTEN has been evaluated in different types of cancer, this study focused on KISS1, a newly identified target gene in which there was no study to determine its association with Let‐7i." (PMID 34096173, 2021). "Moreover, the C-X-C motif chemokine receptor 7 signaling in cancer cells upregulates the expression and release of MMP2 and MMP9 into the extracellular matrix." (PMID 34588926, 2021). "High levels of MMP9 in the pre-metastatic lung promoted vascular remodeling, while genetic ablation of MMP9 normalized the aberrant vasculature in the lung PMN, impeding cancer metastasis." (PMID 33413536, 2021). "Although MMP-2 and MMP-9 (gelatinase B) are factors studied in inflammation and cancer, they are not vastly important in skin aging reactions." (PMID 34122721, 2021). "The expressions of Mmp-9 and Tgf-β (makers of invasiveness in advanced cancers) were also not affected by rmFSTL1 treatment." (PMID 33639614, 2021). "We also report a significant increase in the mRNA expression of MMP-9, -11 and -14 in Stage IV and in Type 2 tumors compared to normal/benign samples may indicate changes in ECM modelling as a prerequisite for cancer progression." (PMID 35047406, 2021). "Therefore, the intratumor activity of both MMP-9 and MMP-2, that are involved in facilitating cancer cell dissemination at secondary sites, was investigated by zymography." (PMID 34764332, 2021). "The risk of macrophages high density, high microvessel density (MVD), low neomicrovessel maturation, MMP-9 expression and low type IV collagen was elevated after LOX overexpression, suggesting that LOX activated cancer stromal cells and facilitated the progression of GC." (PMID 35126449, 2021). "MMP9, for example, is responsible for the shedding of MHC class I antigen from cancer cells." (PMID 34503307, 2021). "Apart from this regulatory axis, we also found evidence of a GAG- and ERK-independent mechanism involving upregulation of another SRGN-binding partner, i.e. MMP9, which might contribute to SRGN-induced cancer cell invasiveness." (PMID 33456569, 2021). "While NO can activate MMP-9 in rat retinal neurons, the NO donor spermine-NONOate decreases MMP-9 activity in endothelial and carcinoma co-cultures." (PMID 33923477, 2021). "An interesting finding is MMP9, MYC, MAPK1, MTOR are all in Proteoglycans in cancer." (PMID 32958005, 2020). "MMP‐9 and MMP‐2 are two key family members of MMPs that are able to degrade the basement membranes and extracellular matrix, and thus facilitate invasion and metastasis of malignant tumour cells into other organs or tissues." (PMID 32237037, 2020).